CFTR (CF transmembrane conductance regulator)
Diseases named in the same sentence as CFTR in open-access papers (continued):
Sharing a sentence is not in itself a finding about the gene and the disease.
diarrheal disease (6 papers, 2013 to 2026). The condition of having at least three loose or liquid bowel movements each day. "CFTR may also be involved in other human diarrheal disease symptoms associated with bacterial and viral infection, neoplasm, or congenital inflammatory conditions." (PMID 35324722, 2022). "The compound (R)-BPO-27 has shown great promise as a potential therapy for diarrheal disease driven by activation of the CFTR channel." (PMID 35324722, 2022). "Further studies are needed that deal with how to make use of the understanding of NHE3, DRA, and CFTR regulation in this cell population to deal with diarrheal diseases and constipation." (PMID 35928564, 2022). "Furthermore, because of the crosstalk between cyclic nucleotide and calcium signaling in enterocytes, compounds that inhibit both CaCC and CFTR might be beneficial in multifactorial diarrheal diseases." (PMID 31649543, 2019).
fungal infection (6 papers, 2006 to 2023). "Lung epithelial CFTR dysfunction leads to dysregulation of epithelial electrolyte flux and build-up of hyperviscous mucus, increasing risk of respiratory bacterial and fungal infection." (PMID 37680748, 2023). "In order to study the effects of Myr on the immune response against fungal infection in CF, monocytes derived from the PBMCs of CF patients bearing homozygous or heterozygous ΔF508 CFTR mutation were infected in vitro with A. fumigatus and either treated or not treated with Myr." (PMID 32781626, 2020). "The onset of highly effective CFTR modulator therapy has improved pulmonary function and mucociliary clearance in many CF patients, however, beneficial outcomes on fungal infections remain to be seen." (PMID 37680748, 2023). "We show that, in the absence of any detectable bacterial and fungal infection, young adult female CF mice generated in the 129/FVB background and homozygous for the most common CFTR gene mutation ΔF508 exhibit a spontaneous lung inflammatory status." (PMID 17064416, 2006).
Hypertension (6 papers, 2012 to 2025). The presence of chronic increased pressure in the systemic arterial system. "We performed electrophysiological, biochemical and fluorescence experiments to evaluate the influence of the hypertension-linked human G460W-S586C adducin variant (G460W adducin) on CFTR activity, expression and trafficking." (PMID 23284854, 2012). "Actually it has already been proposed that an enhancement of CFTR activity could be involved in hypertension and in hypertension related pathologies, such as Liddle syndrome." (PMID 23284854, 2012). "The experiments evidenced that the mutation of adducin in MHS rat DCT cells correlates with an increased CFTR channel density and activity, suggesting that CFTR could be directly or indirectly involved in the general alteration of renal ion transport in essential hypertension." (PMID 23284854, 2012). "According to the models built, both drugs were able to modulate common pathways through their common off-target binding, but ibrutinib modulated more strongly proteins involved in hypertension, such as CXCR3 and CFTR." (PMID 40744952, 2025).
Obstructive azoospermia (6 papers, 2012 to 2023). Absence of any measurable level of sperm in his semen, resulting from post-testicular obstruction or retrograde ejaculation. "Men with obstructive azoospermia (OA) due to impaired development of the genital tract often carry at least one Cystic Fibrosis Transmembrane Conductance Regulator CFTR mutation." (PMID 33095972, 2021).
pancreatic adenocarcinoma (6 papers, 2011 to 2025). "Here we identify the cis‐regulatory elements (CREs) associated with the CFTR locus by open chromatin mapping in pancreatic adenocarcinoma cell lines, primary human pancreatic and bile duct (cholangiocyte) organoids and single cells from tissues, as well as sweat gland coil and duct epithelial cells." (PMID 40785146, 2025). "Capan-1 cells are pancreatic duct epithelial cells derived from pancreatic adenocarcinoma that express the CFTR gene." (PMID 40332394, 2025). "In 2009, NEDD4L (also known as Nedd4-2) was identified as another ubiquitin ligase capable of interacting with both WT- and F508del-CFTR in CFPAC-1 cells (a pancreatic adenocarcinoma cell line from a patient carrying F508del-CFTR)." (PMID 38888668, 2024). "In vitro, eluforsen improved chloride efflux in CF pancreatic adenocarcinoma cell cultures and increased short-circuit current in primary human bronchial epithelial cells, both indicating restoration of CFTR function." (PMID 31251792, 2019). "Using Capan-1, a pancreas adenocarcinoma cell line, which express endogenous CFTR, they showed that Ca2+ signals activate the Cl- dependent HCO3- transport of CFTR." (PMID 30618777, 2018). "In earlier surveys of pancreatic adenocarcinoma cell lines by RT‐qPCR, we found CFTR mRNA only in Capan‐1 and NP31 cells and not in BxPC‐3 or seven other pancreatic adenocarcinoma cell lines." (PMID 40785146, 2025).
protein folding disease (6 papers, 2013 to 2025). "CF is a proteinopathy caused by loss-of-function mutations in the CF transmembrane conductance regulator (CFTR) protein, a cAMP-regulated chloride channel expressed primarily at the apical plasma membrane of secretory epithelia in the airways, pancreas, intestine, and other tissues." (PMID 39959972, 2025). "This latter observation indicates that reducing inflammatory lipid accumulation and promoting autophagy is an effective therapeutic approach to correcting proteinopathy stress, mainly related to ΔF508 mutation of CFTR, and to restoring an effective response against infection." (PMID 32781626, 2020). "Thus, the HTS assay reported here could be useful in studying additional CFTR mutations or adapting for use in other protein folding disorders or drug discovery efforts." (PMID 35169219, 2022). "Stabilizing CFTR mutants at the cell surface after pharmacological rescue is an important goal of CF research and strategies that are successful for CFTR mutants may be applicable to other protein folding diseases." (PMID 35060604, 2022).
typhoid fever (6 papers, 2005 to 2024). A bacterial infectious disorder contracted by consumption of food or drink contaminated with Salmonella typhi. "The gene was recently found to code for chloride ion protein-channels on somatic epithelial cell membranes, and the bacteria causing typhoid fever, Salmonella enterica serovar Typhi, was found to target the CFTR protein in GI cells to gain entry to them." (PMID 15885137, 2005). "The susceptibility to typhoid fever is associated with a polymorphism in the cystic fibrosis transmembrane conductance regulator (CFTR), while genetic associations of a member of the tripartite motif (TRIM) family with human immunodeficiency virus type 1 infection have been reported." (PMID 24934404, 2014). "Afterward, S. Typhi might induce more intestinal epithelial cells to express its CFTR protein and this could be an essential step for the development of typhoid fever." (PMID 33562108, 2021).
aspergillosis (5 papers, 2022 to 2025). Aspergillosis is an infection, growth, or allergic response caused by the Aspergillus fungus. "Here, utilising CFTR deficient mice we describe a hyperinflammatory phenotype in both acute and allergic murine models of pulmonary aspergillosis." (PMID 39903773, 2025). "We show that during aspergillosis, CFTR deficiency leads to increased alveolar macrophage death and persistent inflammation of the airways in CF, accompanied by impaired fungal control." (PMID 39903773, 2025). "Taken together, these studies indicate that CFTR deficiency promotes increased activation of inflammatory pathways, the induction of macrophage cell death and reduced fungal control contributing to the hyper-inflammatory of pulmonary aspergillosis phenotypes in CF." (PMID 39903773, 2025). "In both the acute and allergic models of aspergillosis, CFTR-/- mice lost more weight than the WT control group suggesting that infection with A. fumigatus induced a more potent and prolonged inflammatory response in the CFTR-/- mice compared to wild type." (PMID 39903773, 2025). "To further expand our knowledge about ABPA cases during CFTR modulator therapy, we performed a thorough literature search in the PubMed online library with search terms “eosinophilia”, “fungus”, “allergic”, “CFTR modulator”, “aspergillosis”, “Aspergillus”, and “ABPA” including CFTR clinical trials." (PMID 39330416, 2024).
asthenozoospermia (5 papers, 2015 to 2023). "Genetic defects in CatSper1/2 and in the sperm-specific anion exchanger SLC26A8 that associates with the CFTR channel, have been identified in patients affected by distinct types of asthenozoospermia." (PMID 34205849, 2021). "Variants in SLC26A8 have been implicated to cause asthenozoospermia (reduced sperm motility) via altered interaction with CFTR (cystic fibrosis transmembrane conductance regulator)." (PMID 26261983, 2015).
atherosclerosis (5 papers, 2017 to 2025). A disease characterized by the build-up of fatty material and calcium deposition in the arterial wall resulting in partial or complete occlusion of the arterial lumen. "Therefore, in the present study, we investigated whether CFTR is causally involved in atherosclerosis-related inflammation as well as atherogenesis and if so, to clarify its mechanism in these processes." (PMID 28615349, 2017). "These works together with our present study suggest that CFTR prevents atherosclerosis development through inhibiting vascular inflammation rather than influencing lipid transport." (PMID 28615349, 2017). "To investigate the impact of atherosclerosis on CFTR expression in the vasculature, we analyzed CFTR level in mouse atherosclerotic plaque." (PMID 28615349, 2017). "Up-regulation of CFTR attenuated immune cells infiltration and vascular inflammation as well as atherosclerosis development in apoE−/− mice." (PMID 28615349, 2017). "Consistent with previous studies, our results also supported that CFTR plays an important role in vascular inflammation and atherosclerosis." (PMID 28615349, 2017). "Therefore, improved fat absorption resulting from the action of the CFTR modulator can contribute to the appearance of atherosclerosis and possibly increase insulin resistance, which will favor the appearance of metabolic syndrome." (PMID 36678185, 2023). "The present study suggests that CFTR could be an attractive therapeutic target for the resolution of inflammation and atherosclerosis." (PMID 28615349, 2017). "To test whether the NFκB and MAPKs signaling are involved in CFTR-dependent regulation of inflammation and atherosclerosis, we examined the activities of NFκB and MAPKs in mouse peritoneal macrophages." (PMID 28615349, 2017). "To investigate whether CFTR down-regulation limits the development of atherosclerosis or exerts a proatherogenic role, we used gain-function strategy in vivo." (PMID 28615349, 2017). "However, it is not yet known which is involved in CFTR-regulated vascular inflammation and atherosclerosis." (PMID 28615349, 2017).
autoimmune pancreatitis (5 papers, 2012 to 2025). "In previous studies, we have found that CFTR is largely mislocalized to the cytoplasm of pancreatic duct cells in all forms of CP and corticosteroids normalizes the localization of CFTR to the proper apical membrane at least in autoimmune pancreatitis." (PMID 23133422, 2012). "Furthermore, in a murine autoimmune pancreatitis model, the CFTR corrector C18 rescued CFTR expression and localization in the pancreas." (PMID 35011616, 2021). "In a mouse model of autoimmune pancreatitis, it is worth pointing out that the cystic fibrosis transmembrane conductance regulator (CFTR) corrector C18 and the CFTR potentiator VX770 rescued CFTR expression, restored AQP5 expression and pancreatic fluid secretion, and eliminated tissue inflammation." (PMID 31614661, 2019).
biliary cirrhosis (5 papers, 2016 to 2025). "The conventional hypothesis includes CFTR dysfunction in the biliary epithelial cells, causing thick, tenacious bile leading to focal biliary cirrhosis, which may later progress to multifocal biliary cirrhosis." (PMID 33671639, 2021).
Chronic constipation (5 papers, 2020 to 2025). Constipation for longer than three months with fewer than 3 bowel movements per week, straining, lumpy or hard stools, and a sensation of anorectal obstruction or incomplete defecation. "While chronic constipation has a complex, multifactorial etiology, CFTR plays a pivotal role as a regulator of intestinal ion and fluid balance and serves as a therapeutic target in constipation management." (PMID 40066329, 2025). "LBP facilitates fluid secretion by activating CFTR in the intestine and is used as a drug for treating chronic constipation." (PMID 32306956, 2020). "In the intestinal epithelium, LBP promotes intracellular Cl− and fluid secretion to the intestinal tract through the activation of CFTR due to prostanoid receptor signaling; therefore, LBP is used as a chronic constipation drug." (PMID 32306956, 2020).
Cirrhosis (5 papers, 2013 to 2026). A chronic disorder of the liver in which liver tissue becomes scarred and is partially replaced by regenerative nodules and fibrotic tissue resulting in loss of liver function. "Ramsey and colleagues also noted that patients on CFTR modulators alone had a lower incidence of development of cirrhosis or acute liver failure overall than their untreated counterparts." (PMID 40980774, 2025). "It is unknown why only a subset of CF patients develops cirrhosis, while the majority of individuals with a similar CFTR defect do not develop cirrhosis." (PMID 24171010, 2013).
colitis (5 papers, 2010 to 2023). Inflammation of the colon. "More importantly, a body tissue chloride ion influx in high fat-fed rats is found in Lactobacillus casei intervention group and subsequently this probiotic can prevent colitis by activating chloride ion dependent channel CFTR in mice." (PMID 35433778, 2022). "In this study, we identified a subpopulation of COX-expressing MSCs that promote intestinal organoid swelling via PGE2 secretion to activate CFTR, support the Muc2 expression of intestinal epithelium, and confer the epithelium resistance to injury in the DSS-induced colitis model." (PMID 37574502, 2023). "Intriguingly, induction of colitis in Cftr knockout mice leads to bile duct injury, and reduced CFTR function have been reported in PSC patients, even in the absence of CFTR mutations." (PMID 20811628, 2010). "The link between enteric microbes and inflammatory cholangiopathies has been observed in mice lacking the expression of functional CFTR (CFTR−/−) and subjected to dextran sodium sulfate (DSS) colitis model." (PMID 30275402, 2018).
colorectal adenocarcinoma (5 papers, 2015 to 2025). The most common type of colorectal carcinoma. "In order to confirm that promotion of cell death by FAC and erastin is related to the loss of CFTR function, we investigated the effects of the CFTR inhibitors CFTR(inh)-172 and GlyH-101 on immortalised human colorectal adenocarcinoma cells (Caco-2)." (PMID 34903297, 2021). "As CFTR is the main ion channel in the colon, where it regulates fluid filling, we first tested whether lumen expansion in Caco-2 colorectal adenocarcinoma cells was dependent on CFTR." (PMID 35997536, 2022). "The i10c CRE (Refseq i11iii) was first identified as a site of open chromatin in Caco2 cells, a colorectal adenocarcinoma cell line which expresses CFTR, however, it lacked enhancer activity in these cells; moreover, it was evident in skin fibroblasts that do not express CFTR." (PMID 37269165, 2023).
deafness (5 papers, 2013 to 2025). An inherited or acquired condition characterized by the complete loss of the ability to hear from one or both ears. "These include (i) rs113993960 variant in CFTR leading to the deletion of a crucial F508 residue of the CFTR protein, and (ii) rs80338939 variant in GJB2 linked to hearing loss and deafness." (PMID 39498263, 2024). "In Romania, the national neonatal metabolic screening program currently covers three disorders, corresponding to CFTR, PAH and hypothyroidism, together with clinical screening for deafness." (PMID 41303398, 2025).
dry eye (5 papers, 2021 to 2024). "In this study, we performed a cell-based, high-throughput screening for the identification of novel natural products that activate CFTR and restore the aqueous deficiency in dry eye." (PMID 33921231, 2021). "Isorhamnetin may be a potential agent for the treatment of dry eye caused by lacrimal gland dysfunction in patients with Sjogren’s syndrome because it can induce water secretion via CFTR activation in ocular surface epithelium and has anti-inflammatory effect via its antioxidative activity." (PMID 33921231, 2021). "In this study, we identified a novel CFTR activator, isorhamnetin, and investigated the effectiveness of isorhamnetin in an experimental mouse model of dry eye." (PMID 33921231, 2021). "However, the intracellular cAMP in the conjunctiva was decreased in the eDED model, indicating that the CFTR signaling was impaired in the dry eye condition." (PMID 36430877, 2022). "Interestingly, topical treatment of IBMX, which stimulates CFTR by elevating the intracellular cAMP, on patients with dry eye resulted in an increase in tear secretion and decrease in tear film osmolarity." (PMID 33921231, 2021). "Therefore, CFTR activators that induce a sustained fluid secretion from the ocular surface epithelium may be more useful in the treatment of patients with dry eye than CaCC activators or ENaC inhibitors." (PMID 35563597, 2022). "However, there was no discernible relationship between the expression of CFTR and markers of disease activity (except C4), gender, age, dry eye state, dry eye test, and other autoantibody levels." (PMID 36476557, 2022).
gastric cancer (5 papers, 2017 to 2023). A primary or metastatic malignant neoplasm involving the stomach. "Various other molecular pathways have been implicated in the association between CFTR dysfunction and gastric cancer development." (PMID 37686519, 2023). "Therefore, the association between CF, CFTR, and gastric cancer involves complex molecular mechanisms." (PMID 37686519, 2023). "In addition to CFTR mutations, CF-related genetic variations may contribute to the increased risk of gastric cancer." (PMID 37686519, 2023). "There is also one report that serum CFTR levels correlated with the serum expression of the tumor biomarker CA199 in gastric cancer." (PMID 35743652, 2022).
Hypoglycemia (5 papers, 2021 to 2026). A decreased concentration of glucose in the blood. "While CFTR modulators have improved glycemic control in some individuals, they have also been associated with hypoglycemia, highlighting the need for close monitoring and further research to clarify these effects." (PMID 41552835, 2026). "The EPHA5 and CFTR proteins are both implicated as functioning in the ventromedial hypothalamus (VMH) at the level of synaptic neuron-glia in response to hypoglycemia by enhancing glutamatergic neurotransmission." (PMID 33572894, 2021). "CFTR modulators effect on hypoglycemia: CFTR modulators, particularly ivacaftor (IVA), have been shown to improve insulin secretion in PwCF—most notably in those carrying gating mutations such as G551D—suggesting potential restoration of islet function and improved glucose regulation." (PMID 41552835, 2026). "While there have been concerns that CFTR modulator therapies may lead to increased incidents of hypoglycemia, this has not been the case in the studies that have been performed to date." (PMID 37575762, 2023).
hypogonadism (5 papers, 2020 to 2025). A disorder characterized by decreased function of the gonads. "Among the main risk factors for bone loss in CF are poor nutritional status, vitamin D and K deficiencies, calcium, hypogonadism, glucocorticoid use, physical inactivity, CFTR dysfunction, and exacerbations of lung infections." (PMID 33143143, 2020).